IL6 (interleukin 6)
Diseases named in the same sentence as IL6 in open-access papers (continued):
Sharing a sentence is not in itself a finding about the gene and the disease.
psoriasis vulgaris (12 papers, 2006 to 2025). Plaque psoriasis is the most common presentation of psoriasis. "While the IL23/Th17 pathway is responsible for the development of psoriasis vulgaris, IL-1, IL-36, and IL-6 are the cytokines known to be involved in the development of pustular psoriasis." (PMID 32811699, 2020). "First, we were unable to measure the progression of psoriasis vulgaris of blood-heat syndrome using serum markers in pretherapeutic patients, and only three/four eligible observation studies that reported serum IL-23/IL-6 levels were reviewed." (PMID 27274756, 2016). "The cytokines from the psoriatic plaque spread into the circulation, which was represented by high serum levels of TNF-α downstream cytokines, IL-6 and IL-8, in thick plaque psoriasis." (PMID 26176783, 2015). "In this study, the cross-sectional study identified the fact that serum CRP, IL-2, IL-6, TNF-α and IFN-γ levels were significantly increased in PsA patients, and positive serum CRP, IL-6 and TNF-α were independently associated with PsA among psoriasis vulgaris patients." (PMID 39335643, 2024). "Thus, we established a simple score scale composed of serum CRP, IL-6 and TNF-α levels to estimate the risk for progressing to PsA among psoriasis vulgaris patients, and validated the scale internally and for a retrospective cohort." (PMID 39335643, 2024). "Studies found that the increased Th2 and Th17 immune response may play a role in EP pathogenesis, endorsed by the higher serum level of interleukin (IL)-13, IL-4, IL-6 and IL-10 in EP patients than patients with plaque psoriasis." (PMID 34970217, 2021). "In both GPP and plaque psoriasis, defects in inflammatory mediators that are involved in allergic rhinoconjunctivitis, including pro‐inflammatory IL (specifically IL‐6) and TNF‐α,16, 17 also contribute to the manifestation of GPP and plaque psoriasis." (PMID 34390028, 2021). "Meta-analysis of the results for all markers, including IFN-γ, IL-4, IL-17, IL-23, IL-6, TNF-α, and IL-10, for subjects with psoriasis vulgaris of blood-heat syndrome revealed significant between-study heterogeneity (I2 > 75%) with random-effects modeling." (PMID 27274756, 2016). "Serum levels of the inflammatory mediators IL-6, IL-8, IL-12, IL-18, TNF-α and INF-γ were found to be elevated in plaque psoriasis." (PMID 24651659, 2014). "The simple score, composed of CRP, IL-6 and TNF-α, with the cut-off value of 1.8, also showed satisfying predictive performance for PsA among the retrospective cohort of psoriasis vulgaris patients externally (AUC = 0.686, p = 0.010, sensitivity = 59.1%, specificity = 78.1%)." (PMID 39335643, 2024). "Furthermore, IL-29 up-regulated the mRNA expression levels of IL-6, IL-17 and TNF-α in PBMCs from psoriasis vulgaris patients." (PMID 34030913, 2021). "In vitro and in vivo animal experiments show that the EPS/CPT emulsion can effectively treat psoriasis vulgaris by increasing the accumulation of CPT in psoriatic skin lesions and reducing the levels of inflammatory cells and inflammatory factors (TNF and IL6)." (PMID 31861934, 2019). "We performed a systematic review and meta-analysis to determine whether seven well-known immunological serum markers (IFN-γ, IL-4, IL-17, IL-23, IL-6, TNF-α, and IL-10) are elevated or decreased in patients with psoriasis vulgaris of blood-heat syndrome compared with controls." (PMID 27274756, 2016). "In the retrospective cohort, the previous results of serum CRP, IL-6, and TNF-α detection were collected for the included psoriasis vulgaris patients who did not progress into PsA, and the clinical prognosis was followed up for at least 4 years." (PMID 39335643, 2024). "As for the technological restriction, only a few psoriasis vulgaris patients showed serum CRP, IL-6 and TNF-α detected previously, so most patients could not be included in this retrospective cohort." (PMID 39335643, 2024).
psoriasis vulgaris (continued). "We conducted a cross-sectional study to compare the levels of serum inflammatory indicators between psoriasis vulgaris patients who progressed to PsA and those who did not, and found that CRP, IL6 and TNF-α levels were all higher in PsA patients than in controls." (PMID 39335643, 2024).
pyelonephritis (12 papers, 2009 to 2025). An inflammatory process affecting the kidney. "Another researcher confirmed that serum levels of IL-6 were more sensitive and specific than IL-8 for the diagnosis of pyelonephritis." (PMID 36779185, 2023). "Further investigations with definite tendency of increase of the number of participants suffering from the common health disorder of pyelonephritis will contribute to proper evaluation of mRNA levels of IL-6, MMP-8 and GSS as salivary biomarkers." (PMID 31881666, 2019). "The low rate of impingement of the epithelial tissue in the state of pyelonephritis corresponds to the obtained results illustrating a correlation between blood in urine on one hand, and IL-6 and GSS in saliva, on the other." (PMID 31881666, 2019). "Serum IL-6 was 67.5 ± 75.4 pg/ml (mean ± standard deviation [SD]) in the pyelonephritis group, 12.1 ± 15.0 pg/ml in the lower UTI group and 1.6 to 2.8 pg/ml in the healthy controls, P < 0.001." (PMID 19707519, 2009). "Urine IL-6 was 516 ± 685.9 pg/mg of creatinine (mean ± SD) in the pyelonephritis group, 46.9 ± 78.8 pg/mg in lower UTI group and was undetectable in healthy control group, P < 0.001." (PMID 19707519, 2009). "Similarly, in the pyelonephritis mice model, higher mortality in IL6 knockout mice was found when infected with E. coli CFT073 strain." (PMID 35604916, 2022). "Salivary IL-6, MMP-8 and GSS mRNA levels in combination with urine test analysis could be useful diagnostic tool for the very distributed disorder of pyelonephritis in childhood." (PMID 31881666, 2019). "Salivary IL-6, MMP-8 and GSS mRNA levels in combination with urine test analysis could be a useful diagnostic tool for the very distributed disorder of pyelonephritis in childhood." (PMID 31881666, 2019). "In pyelonephritis, proinflammatory cytokines, such as Tumor Necrosis Factor-α (TNF-α), Monocyte Chemoattractant Protein-1 (MCP-1), Interleukin-6 (IL-6), IL-8 and IL-23, play an important role in mounting the immune response." (PMID 37371050, 2023). "In a pilot study on pregnant women, CB juice consumption reduced urinary IL-6, which has been suggested for differentiating between lower UTI and pyelonephritis." (PMID 33194008, 2020). "We recorded that the mRNA levels of the pro-inflammatory cytokine IL-6 were considerably higher compared to these of MMP-8 and GSS for all 28 children with pyelonephritis." (PMID 31881666, 2019). "Analysis of the mRNA levels for IL-6, MMP-8 and GSS in 28 children hospitalized with the diagnosis of pyelonephritis was conducted applying the method of quantitative reverse transcription polymerase chain reaction (RT-qPCR)." (PMID 31881666, 2019). "Interleukin 6 has also shown some promise in differentiating between lower UTI and pyelonephritis but needs further validation." (PMID 19707519, 2009). "Interleukin 6 (IL-6) and interleukin 8 (IL-8) have been studied in adults to diagnose UTI and in children to differentiate between pyelonephritis and lower UTI." (PMID 19707519, 2009). "Among all 28 participants with diagnosed pyelonephritis, nine showed considerably high mRNA levels of IL-6, MMP-8 and GSS (Patients No 1, 12, 16, 17, 19, 21, 23, 24, 28)." (PMID 31881666, 2019). "IL-6 and IL-8 have been studied in several settings including diagnosing UTI in adults in the postoperative setting, in diagnosing bacterial UTI in children, and in diagnosing pyelonephritis in children." (PMID 19707519, 2009).
spondyloarthritis (12 papers, 2008 to 2025). "Cytokine-mediated inflammation involving IL-1/NLRP3, TNF-α, IL-6, and IL-17 pathways has been implicated in both spondyloarthritis and pericardial disease." (PMID 41357030, 2025). "JAK inhibitors modulate multiple inflammatory pathways by suppressing key cytokines, including IL-6, IL-12, and IL-23, which are implicated in the pathogenesis of both spondyloarthritis and ocular inflammation." (PMID 41208989, 2025). "Serum interleukin 6 (IL-6) and interleukin 23 (IL-23) are considered to be associated with the inflammatory process in spondyloarthritis." (PMID 27527149, 2016). "Also, a prior proteomic study on the spondyloarthropathy implicated MNDA as a meaningful biomarker to detect inflammatory responses earlier than other markers such as IL-6 and CRP63." (PMID 36804462, 2023). "A study found a correlation between atherogenic indexes and both IL-1 and IL-6 as a result of spondyloarthritis, and that serum IL-6 and IL-1 levels contribute to the development of AS." (PMID 37077636, 2023). "In endoscopic mucosal samples, IBD similarly exhibits a strong TH1 phenotype in early lesions and switches to a TH17 phenotype, with marked increase in IL-17A, and induction of IL-6 and IL-23; it can occur subsequent to different categories of JIA as well as spondyloarthropathies." (PMID 28288653, 2017).
ST Elevation Myocardial Infarction (12 papers, 2019 to 2026). A myocardial infarction that produces elevation in the ST segments of the ECG. "Higher IL-6 levels, particularly following ST-elevation myocardial infarction (STEMI), are linked to larger infarct sizes and reduced cardiac function, making IL-6 a potential biomarker for STEMI prognosis." (PMID 40244022, 2025). "We studied the association of the interleukin 6 (IL-6) cascade with infarct size and cardiac function after ST-elevation myocardial infarction (STEMI)." (PMID 30367209, 2019). "FAM20A, a secreted pseudo kinase essential for biomineralization, regulates calcium-phosphate metabolism and is known to be upregulated in conditions such as ST-elevation myocardial infarction, also via the IL-6/JAK/STAT3 signaling." (PMID 40877937, 2025). "Similarly, positive results have been reported by studies assessing the effect of tocilizumab (anti-IL-6 antibody) on reducing the ischemic area in patients with ST-elevation myocardial infarction." (PMID 35630041, 2022). "PTX3, IL-6 and hs-CRP were measured at predefined time points, at baseline(before percutaneous coronary intervention (PCI)), at 12 and 72 hours afterPCI in 161 patients with first-time ST elevation myocardial infarction(STEMI)." (PMID 32403934, 2020).
Ureteral obstruction (12 papers, 2012 to 2025). Obstruction of the flow of urine through the ureter. "EVs extracted from bone marrow-derived MSCs showed an increase in IL-10 with attenuation of macrophages as well as IL-6 in a ureteric obstruction model." (PMID 40535418, 2025). "The P2X7R promotes the release of IL-6 and TNF from mouse microglia, which are implicated in tubular fibrosis and apoptosis in response to ureteral obstruction in mice." (PMID 35530034, 2022). "For example, ureteral obstruction caused a significant upregulation of the mRNA expression of TNF-α, PAI-1, IL-6, and IL-1β (2.22 ± 0.47 vs. 1.03 ± 0.11, 5.38 ± 0.87 vs. 1.02 ± 0.10, 10.35 ± 1.42 vs. 1.00 ± 0.21 and 1.55 ± 0.07 vs. 0.99 ± 0., respectively, p < 0.05 for all)." (PMID 39457599, 2024). "IL-6 could distinguish bilateral ureteral obstruction, with an AUC of 0.861 (95% CI: 0.682-1.000, p=0.015)." (PMID 36524110, 2022). "Higher expression levels of PDGF, TGF-β, IGF-I, IL-6 have been reported after ureteral obstruction." (PMID 24023933, 2013). "In kidneys of mice with ischemia-reperfusion injury or unilateral ureteral obstruction, the loss of ACE2 exacerbated infiltration of neutrophils, F4/80+ macrophages, and CD3+ T cells, and increased mRNA levels of cytokines and chemokines, including IL6, TNF, and MCP-1." (PMID 33125431, 2020). "A study showed that the expression of IL-1β, IL-6, IL-18, and TNF-α in peripheral blood and renal tissues of rats with unilateral ureteral obstruction was significantly reduced by DSF." (PMID 35563653, 2022). "In conclusion, glomerular miR-21 expression is elevated following unilateral ureteral obstruction, wherein it interacts with TLR8 in podocytes and induces production of downstream cytokines (Il1b and Il6) suggesting activation of NF-κB pathway." (PMID 33552064, 2020). "Many growth factors and cytokines were overexpressed after ureteral obstruction, including platelet-derived growth factor (PDGF), transforming growth factor-beta (TGF-β), insulin-like growth factor-I (IGF-I), Interleukin-6 (IL-6)." (PMID 24023933, 2013). "According to the presence or absence of bilateral ureteral obstruction, the AUC for IL-6 was 0.861 (sensitivity 0.833 and specificity 0.833, p=0.015).." (PMID 36524110, 2022). "After the onset of unilateral ureteral obstruction, IL-10 knockout mice show increased infiltration of inflammatory cells and cytokines, including monocyte chemoattractant protein-1, TNF-α, IL-6, IL-8, RANTES, or macrophage colony-stimulating factor, in the kidney compared with WT controls." (PMID 31194740, 2019).
ventilator-associated pneumonia (12 papers, 2005 to 2025). Serious INFLAMMATION of the LUNG in patients who required the use of PULMONARY VENTILATOR. "Combination of TLR4 and TIRAP SNPs has been described to be associated with low circulating levels of TNF-α and IL-6 in adult patients with ventilator-associated pneumonia following 1 ng/ml LPS-stimulation." (PMID 30131804, 2018). "The changes in the mean levels of glutathione peroxidase (GPX) activity, IL-6, IL-8 and IL-10, the incidence of ventilator-associated pneumonia (VAP) and other secondary endpoints were also recorded." (PMID 26429356, 2015). "In a ventilator-associated pneumonia mouse model caused by Acinetobacter baumannii, AZM (10 or 100 mg/kg) reduced the neutrophil influx and the release of IL-1β, IL-6, and CXCL2 in BALF." (PMID 35972289, 2022). "In mechanically ventilated adults with burn injury, IL-8 (but not IL-6 after adjustment) independently predicted ventilator-associated pneumonia (VAP) and mortality, with levels measured on days 0, 3, and 7 remaining significant predictors of poor outcomes." (PMID 41155423, 2025). "In intubated burn patients, IL-8 (but not IL-6 after adjustment) independently predicted ventilator-associated pneumonia (VAP) and mortality; IL-8-centric risk persisted at serial time points." (PMID 41155423, 2025). "Furthermore, neither the predictive value of pepsin in TS for early ventilator-associated pneumonia nor the analysis of uric acid, IL-6, and glucose distribution in TS as potential biomarkers for early AP diagnosis yielded statistically significant results." (PMID 37685534, 2023).
acute pyelonephritis (11 papers, 2009 to 2023). "Scientific literature confirms that children affected by acute pyelonephritis are characterized with high serum or urine levels of IL-6, which can serve as an indicator of renal damage and is a parameter related to its progression." (PMID 31881666, 2019). "Sensitivity, specificity and predictive value of urinary interleukin-6 (uIL-6) in the diagnosis of acute pyelonephritis (APN)." (PMID 27564295, 2016). "Rapid decline of IL-6 was demonstrated in the sera of females with acute pyelonephritis due to Escherichia coli, who were treated with broad spectrum antibiotics." (PMID 23690657, 2013). "Early work showed that acute pyelonephritis is accompanied by an increase in urine IL-6 compared to ABU and IL-8 levels showed a similar pattern, defining ABU as a condition with low mucosal host response induction." (PMID 22140570, 2011). "Currently, there are discrepant results when using urinary IL-6, serum and urinary IL-8 to diagnose acute pyelonephritis in children and adults." (PMID 19707519, 2009). "Serum IL-6 is a possible novel biomarker to diagnose acute pyelonephritis in children but further studies are warranted." (PMID 19707519, 2009). "Procalcitonin (PCT), interleukin 6 (IL-6), and interleukin 8 (IL-8) have been studied to diagnose acute pyelonephritis at an early stage." (PMID 19707519, 2009). "Serum and urine IL-6 and IL-8 levels may be useful for rapid detection of acute pyelonephritis in febrile children." (PMID 20550702, 2010). "In the present study, we have examined the mRNA levels of IL-6, MMP-8 and GSS using saliva as an emerging, non-invasive and perspective medium for precise diagnosis of acute pyelonephritis in children." (PMID 31881666, 2019). "On the other hand, the same research group previously found that there is a significant elevation of serum and urinary levels of IL-6 and CXCL8/IL-8 in children with acute pyelonephritis when compared to children with lower urinary tract infection." (PMID 24066006, 2013). "Higher or similar fold-plasma concentrations (4 to 75-fold) of IL-6 have been observed in non-pregnant women with acute pyelonephritis vs. patients with asymptomatic bacteriuria, after acute pyelonephritis treatment or healthy volunteers." (PMID 37896187, 2023). "For example, in non-pregnant women with acute pyelonephritis, the plasma concentrations of the pro-inflammatory cytokines IL-6 and IL-8, TNF-α, and protein C reactive (CRP) can reach from 2 to 75 times the concentrations in healthy pregnant and non-pregnant women." (PMID 37896187, 2023). "In general, IL-6 and IL-8 levels are elevated in the urine of patients with UTI and children with acute pyelonephritis, whereas none are measurable in the urine of controls." (PMID 25807366, 2015).
alopecia (11 papers, 2019 to 2025). Hair loss usually from the scalp. "Our results indicated that as the severity of alopecia increased from mild to severe, there was a corresponding increase in the levels of IL-6, TNF-α, IL-17A, and IL-21." (PMID 41002719, 2025). "Interleukin-6 (IL-6) is considered a central marker of chronic inflammation and the progression of various types of alopecia." (PMID 40361941, 2025). "By day 21 post‐IR, IL‐6−/− mice outwardly displayed about a 10‐fold reduction in alopecia with strongly diminished histologically evident hair follicle degeneration and acanthosis in comparison to irradiated WT controls." (PMID 35785521, 2022). "High serum levels of IL-4, IL-5, and IL-6 are also reported in patients with alopecia." (PMID 35273508, 2022). "In an alopecia model, XFZYD can significantly inhibit the levels of IL-6, IL-1β, and TNF-α in serum and skin tissue." (PMID 40430532, 2025). "Thus, IL-6, IL-1, and TNF-α represent a crucial set of pro-inflammatory markers that can be measured to assess alopecia’s severity and the response to PRP treatment." (PMID 40361941, 2025).
Candidemia (11 papers, 2016 to 2024). A form of invasive candidiasis where species of CANDIDA are present in the blood. "In contrast, tocilizumab, an inhibitor of IL-6, has demonstrated an elevated risk in the context of coronavirus disease 2019 (COVID-19) treatment, as evidenced by a 6.9% prevalence of candidemia among patients using the drug." (PMID 38605952, 2024). "A total of 303 patients received IL-6 inhibitors and 12 had Candida infection including five candidemia with tocilizumab (400 mg) after two weeks." (PMID 38605952, 2024). "Further, PCT is considered superior to CRP, serum amyloid A (SAA) and Interleukin (IL)-6 in predicting candidemia." (PMID 29371558, 2017). "The most interesting result of our investigation was the significantly higher levels of the pro-inflammatory Th17 type cytokine, IL17A and IL-6, in the serum samples from patients with candidemia in comparison with samples from patients with bacterial infections and the healthy subjects." (PMID 34684298, 2021). "Importantly, our study did not demonstrate that either IL-6 inhibitor or steroid use was independently associated with candidemia." (PMID 38721496, 2024). "Serum IL-17A and IL-6 levels could not be detected in the healthy control group, whereas, in comparison with the bacterial group, the candidemia group had significantly elevated levels of these cytokines." (PMID 34684298, 2021).